ENSG00000273269 (novel transcript)
Gene: Protein-coding gene on chromosome 2 (47,065,941 to 47,176,511, reverse strand). Ensembl gene ENSG00000273269.
Genetic constraint (gnomAD): Missense variants: 81 observed, 34.71 expected, observed/expected ratio (o/e) 2.33. Synonymous variants: 31 observed, 12.48 expected, observed/expected ratio (o/e) 2.48.